SCARA5 (scavenger receptor class A member 5)
Diseases named in the same sentence as SCARA5 in open-access papers (continued):
Sharing a sentence is not in itself a finding about the gene and the disease.
glioma (2 papers, 2018 to 2022). A benign or malignant brain and spinal cord tumor that arises from glial cells (astrocytes, oligodendrocytes, ependymal cells). "More interestingly, contrary to the previous findings, another tumor study found SCARA5 expression in glioma cells, neuroblasts, and BC." (PMID 35755171, 2022). "The study found that SCARA5 expression is frequently downregulated in liver cancer, breast cancer, lung cancer and glioma." (PMID 30249289, 2018). "The upregulation of SCARA5 expression significantly suppresses cell proliferation in glioma cells." (PMID 30249289, 2018).
lung adenocarcinoma (2 papers, 2021). A carcinoma that arises from the lung and is characterized by the presence of malignant glandular epithelial cells. "Since promoter methylation is one of the common mechanisms for gene silencing, we analyzed the methylation of the SCARA5 promoter in 435 lung squamous cell carcinoma tissues (including 29 normal lung tissues) and 361 lung adenocarcinoma tissues (including 41 normal lung tissues)." (PMID 34150631, 2021).
lung squamous cell carcinoma (2 papers, 2021 to 2024). "SCARA5 seems not to play a major role as a biomarker in squamous cell carcinoma of the lung." (PMID 39000462, 2024).
lymph node metastasis (2 papers, 2020 to 2022). "Then, the multivariate logistic regression analysis demonstrated that SCARA5 expression (OR = 0.537, 95% CI = 0.340‐0.847, P = .008), lymph node metastasis (OR = 1.858, 95% CI = 1.166‐2.959, P = .009), disease stage (OR = 4.129, 95% CI = 2.337‐7.292, P < .001) intensified the risk of tumour growth." (PMID 31989658, 2020). "But remained factors such as gender, lymph node metastasis and extrathyroidal invasion and we could not find their association with the expression of SCARA5." (PMID 31989658, 2020).
pancreatic cancer (2 papers, 2022 to 2023). "In pancreatic cancer, CAF-derived EVs containing elevated levels of miR-331-3p enhance the proliferation migration and invasive potentials of cancer cells by inhibiting scavenger receptor class A member 5 (SCARA5) expression and activation of the focal adhesion kinase (FAK) pathway." (PMID 37046676, 2023).
renal cell carcinoma (2 papers, 2018 to 2022). "For example, the knockdown of SCARA5 can promote cell proliferation in renal cell carcinoma, whereas increased SCARA5 expression inhibits cancer proliferation." (PMID 30249289, 2018).
Sjögren’s syndrome (2 papers, 2021 to 2022). "These disturbances are reminiscent of those found in many human autoimmune connective tissue disorders (Sjogren’s syndrome, lymphocytic interstitial pneumonia), which suggests that defects in fibroblast SCARA5 can underlie some forms of autoimmune diseases." (PMID 35008858, 2021).
autism (1 paper, 2019). Persistent deficits in social interaction and communication and interaction as well as a markedly restricted repertoire of activity and interest as well as repetitive patterns of behavior. "Moreover, increased transcriptome variability of SCARA5 has been observed in the temporal cortex of patents with autism; one can speculate that this pathway participates in the role of SR‐A in microglia inflammatory response, which is observed in some neuropsychiatric diseases." (PMID 31578828, 2019).
cardioembolic stroke (1 paper, 2021). "They reported SCARA5 as a promising target for the treatment of cardioembolic stroke." (PMID 33691789, 2021). "SCARA5 and TNFSF12 had an especially protective effect on cardioembolic stroke." (PMID 33691789, 2021).
cutaneous melanoma (1 paper, 2023). A primary melanoma arising from atypical melanocytes in the skin. "Accordingly, our current study focused on the association of SCARA5 with prognosis in cutaneous malignant melanoma." (PMID 37035142, 2023). "Further multivariate Cox regression analysis showed that SCARA5 expression (p = 0.012) could be an independent prognostic factor for OS in cutaneous malignant melanoma." (PMID 37035142, 2023). "This study suggests that SCARA5 may serve as a therapeutic target and prognostic indicator for cutaneous melanoma." (PMID 37035142, 2023).
diabetic retinopathy (1 paper, 2014). "This decreased expression of Scara5 must be particularly harmful during iron acumulation conditions, such as diabetic retinopathy, where unliganded or incomplete liganded iron is associated with oxidative damage." (PMID 25259650, 2014).
gastric tumor (1 paper, 2021). "Furthermore, upregulation of SCARA5 inhibited gastric tumor growth and metastasis in a xenograft model." (PMID 33758617, 2021).
hemophilia (1 paper, 2022). Hemophilia is a genetic disorder characterized by spontaneous hemorrhage or prolonged bleeding due to factor VIII or IX deficiency. "As can be seen from the existing literature, SCARA5 is associated with conditions that include tumors, inflammation, CVD, hemophilia, retinopathy, bone lesions, connective-tissue disease, and pregnancy." (PMID 35755171, 2022).
Insulin resistance (1 paper, 2024). Increased resistance towards insulin, that is, diminished effectiveness of insulin in reducing blood glucose levels. "Scavenger Receptor Class A Member 5 (SCARA5), TNFRSF12A, GDF-8, and Related Modular Calcium Binding 2 (SMOC2) were associated with insulin resistance markers and steatosis grade." (PMID 39407757, 2024). "MSR1, KYNU, and RBKS, but not SMPD1, were associated with metabolic and liver dysfunction markers, while SCARA5, TNFRSF12A, SMOC2, but not GDF-8, were associated with insulin resistance markers." (PMID 39407757, 2024). "RBKS, but not SMPD1, was associated with metabolic and liver dysfunction markers, while SCARA5, TNFRSF12A, and SMOC2, but not GDF-8, were associated with insulin resistance markers, and steatosis grade in the OB group." (PMID 39407757, 2024).
iron deficiency (1 paper, 2023). "Of note, decreased SCARA5 expression in cardiomyocytes, leading to iron deficiency, was previously shown in failing human hearts." (PMID 36769209, 2023).
liver fibrosis (1 paper, 2025). "Wt1+ fibroblasts displayed distinct expression of genes, such as Scara5, Fbln2, Adgrd1, and Osr1 (encoding the odd-skipped related transcription factor 1) that has been linked to liver fibrosis, and mesenchymal collagen production (Fig. EV3E)." (PMID 40954217, 2025).
malignant melanoma (1 paper, 2023). "This study aimed to determine the association between SCARA5 and melanoma." (PMID 37035142, 2023). "The overall survival (OS) was significantly higher in melanoma with high SCARA5 expression compared with low SCARA5 expression (p < 0.001)." (PMID 37035142, 2023). "We found that SCARA5 expression in malignant melanoma was significantly correlated with immune infiltration levels." (PMID 37035142, 2023). "The results showed that the SCARA5 mRNA expression in melanoma was significantly lower than in adjacent normal skin tissue (p < 0.001)." (PMID 37035142, 2023). "We found that high SCARA5 expression correlated with longer overall survival (OS) in melanoma patients, and SCARA5 was an independent prognostic factor for OS in melanoma patients." (PMID 37035142, 2023). "SCARA5 has significant potential as a prognostic biomarker and as a promising therapeutic target in melanoma." (PMID 37035142, 2023). "Association of scavenger receptor class A member 5 (SCARA5) expression and clinicopathological features in melanoma." (PMID 37035142, 2023). "Moreover, decreased expression of SCARA5 in melanoma correlated with the tumor, node, and metastasis (TNM) stage and recurrence (p < 0.05)." (PMID 37035142, 2023). "Through immune infiltration analysis and GSEA, we demonstrated that SCARA5 also plays a very important role in the tumor immune microenvironment, providing a foothold for future studies on precise and individualized treatment of malignant melanoma." (PMID 37035142, 2023). "Furthermore, SCARA5 expression in melanoma is related to the level of immune infiltration." (PMID 37035142, 2023). "Overwhelming evidence indicates that the malignant melanoma microenvironment contributes to the immunological changes during SKCM progression, suggesting that SCARA5 may play an important role in the immune system." (PMID 37035142, 2023). "No study has hitherto reported the effect of SCARA5 on malignant melanoma." (PMID 37035142, 2023).
Obesity (1 paper, 2017). Accumulation of substantial excess body fat. "The discovery of factors that control SCARA5 expression could further clarify the mechanisms underlying adipogenesis and offer novel insights that could be used to combat obesity and metabolic disease in the modern world." (PMID 29093466, 2017).
oral squamous cell carcinoma (1 paper, 2025). "Retraction of: Huang J, Lv C, Zhao B, Ji Z, Gao Z. SCARA5 inhibits oral squamous cell carcinoma via inactivating the STAT3 and PI3K/AKT signaling pathways." (PMID 41141927, 2025).
papillary thyroid carcinoma (1 paper, 2020). "By whole transcriptome sequencing of paired papillary thyroid carcinoma (PTC) and adjacent thyroid tissues, author discovered that scavenger receptor class A member 5 (SCARA5) might be crucial anti‐oncogene associated with PTC." (PMID 31989658, 2020).
tumor (33 papers, 2014 to 2025). "SCARA5 expression exhibited good diagnostic performance in differentiating tumor and normal tissues." (PMID 37035142, 2023). "High SCARA5 expression was associated with advanced tumor stage (p < 0.001), positive nodal status (p < 0.001) and high Gleason-score (p < 0.001)." (PMID 37443605, 2023). "High SCARA5 expression levels were associated with tumor, node, and metastasis (TNM) stage (T: p = 0.033, N: p = 0.029, M: p = 0.036), and metastasis/recurrence (p = 0.03), while low SCARA5 expression was associated with patient age, sex and tumor location." (PMID 37035142, 2023). "In a summary, the present study investigated the association between SCARA5 and tumour growth in TCGA cohort and local cohort." (PMID 31989658, 2020). "Subsequently, we performed logistic regression analysis to investigate whether SCARA5 expression intensified the risk of tumour sizes in PTC patient." (PMID 31989658, 2020). "Scavenger receptor class A member 5 (SCARA5) is a newly discovered tumor suppressor which inhibits the phosphorylation of AKT and phosphatidylinositol 3-kinase (PI3K) in CRC cells and tumors." (PMID 38994350, 2024). "SCARA5 is a kind of tumor suppressor gene, and its expression is downregulated in many kinds of tumor cells and tissues." (PMID 37035142, 2023). "Upregulation of SCARA5 can significantly inhibit the proliferation, cloning, invasion, and migration of the tumor cell." (PMID 37035142, 2023). "It has been established that the scavenger receptor class A member 5 (SCARA5) functions as a tumor suppressor gene in various cancer types." (PMID 37035142, 2023). "The relationship between SCARA5 expression and tumor-infiltrating immune cells was analyzed using the Tumor IMmune Estimation Resource (TIMER)." (PMID 37035142, 2023). "Within the PDAC cells, miR-331-3p suppressed the axis involving the scavenger receptor class A member 5 (SCARA5) and focal adhesion kinase, thereby promoting tumor cell proliferation, migration, and invasion." (PMID 37490255, 2023). "High SCARA5 expression was detected in 39/93 tumor tissues (41.9%) and low SCARA5 expression in 54/93 tumor samples (58%)." (PMID 37035142, 2023). "During univariate analysis, SCARA5 expression, tumor (T) stage, node (N) stage, metastasis (M) stage, and recurrence correlated with OS (p < 0.05)." (PMID 37035142, 2023). "SCARA5 is believed to play an important role in the development and progression of several different tumor types." (PMID 37443605, 2023). "Second, the results of multiple tumor tissue samples detected in the ATLAS database show high expression of SCARA5 in tumors including BC and CRC." (PMID 35755171, 2022). "Studies published to date on SCARA5's role in tumors have all involved in multiple tumors: the tumor suppressor function of SCARA5 was first discovered in LC, and the functional studies thereof were comprehensive." (PMID 35755171, 2022). "Altogether, these findings and data provide enough evidence to highlight SCARA5 as a tumor suppressor." (PMID 35510828, 2022). "H&E staining was used to evaluate the morphology of the tumors, and the results indicated tumor necrotic cell decreased in the group of overexpression SCARA5." (PMID 36513999, 2022). "Targeting of tumor cells is achieved through the abilities of the transferrin receptor 1 (TfR1) and the Scavenger Receptor Class A Member 5 (SCARA5), overexpressed in cancer cells to recognize APO nanocages." (PMID 33572999, 2021). "As expected, SCARA5 significantly increased the chemosensitivity of tumor cells to 5-fluorouracil, Cisplatin, and Gemcitabine." (PMID 34150631, 2021). "SCARA5 expression inhibits proliferation and migration of tumor cells and is considered a tumor suppressor gene." (PMID 34150631, 2021). "SCARA5 expression was significantly downregulated in tumor tissues compared to normal lung tissues within the MethHC database (p < 0.001)." (PMID 34150631, 2021).
tumor (continued). "In this study, for the first time, we demonstrated that SCARA5 played a tumor suppressor role in GC.We identified that the mRNA and protein levels of SCARA5 were both down-regulated in GC samples and cell lines, and it's consistent with the TCGA database." (PMID 33758617, 2021). "SCARA5 has been observed to be down-regulated expression in GC compared with adjacent non-tumor tissues through microarray 10 and high-throughput RNA-sequencing." (PMID 33758617, 2021). "In conclusion, these results demonstrate that SCARA5 is a potential tumor suppressor that is inhibited by promoter hypermethylation in GC." (PMID 33758617, 2021). "Chemosensitivity assays were used to evaluate the anti-tumor effect of SCARA5 in conjunction with chemotherapeutic drugs." (PMID 34150631, 2021). "Both in vitro and in vivo experiments in this study revealed SCARA5 overexpression induced cell apoptosis, thereby inhibiting tumor growth." (PMID 34417976, 2021). "SCARA5 downregulation was found in human breast cancer tissues and cell lines and correlated with tumor size and metastatic potential." (PMID 33287315, 2020). "In the TCGA cohort, Univariate logistic regression analysis showed that expression of SCARA5 was a significant protective factor for tumour size (odds ratio [OR] = 0.634, 95% confidence interval [CI] = 0.423‐0.951, P = .028)." (PMID 31989658, 2020). "In this study, we examined 57 matched PTC tumour tissue and adjacent normal tissues to testified the function of SCARA5 in PTC." (PMID 31989658, 2020). "After analyse the correlation between SCARA5 expression and clinicopathological features in TCGA database, we discovered that downregulated SCARA5 is significantly connected age (P = .04) and tumour size (P = .032)." (PMID 31989658, 2020). "More intriguingly, there are accumulating studies validated that SCARA5 act as a tumour suppressor in many human cancer." (PMID 31989658, 2020). "Amongst the down-regulated genes, SCARA5 (Scavenger receptor class A member 5) is a candidate tumor suppressor in several malignancies; however, its role in BRCA cell growth and metastasis is still unclear." (PMID 31238876, 2019). "Recent studies have reported that SCARA5 is a tumor suppressor gene and plays an important role in the tumor progression processes." (PMID 30249289, 2018). "Recently, our previous and other studies have revealed that SCARA5 knockdown enhances tumor growth in HCC." (PMID 30249289, 2018). "Scara5 is also downregulated in cancer, and the systemic upregulation of Scara5, through the treatment with Scara5 liposome complex, markedly inhibits tumor growth in mice." (PMID 25259650, 2014). "Moreover, ADCs polarize tumour-associated macrophages (TAMs) towards pro-inflammatory M1 phenotypes by upregulating toll-like receptor 4 (TLR4) and suppressing scavenger receptor class A member 5 (SCARA5), thereby enhancing phagocytosis and IL-12 secretion." (PMID 40909270, 2025). "We also studied whether SCARA5 DNA methylation could be detected in circulating-free DNA (cfDNA) in a sub-cohort of GUHV where we had both tumor and plasma samples available." (PMID 39488528, 2024). "Indeed, more clinical information on tumor progression and prognosis is warranted to better understand the relationship between SCARA5 and SKCM." (PMID 37035142, 2023). "SCARA5 has been shown to act as a tumor suppressor gene to suppress various cancers." (PMID 37035142, 2023). "And some researches revealed that SCARA5 was essential for tumor metastasis and invasion." (PMID 36513999, 2022). "SCARA5 has been reported to act as a tumor suppressor in many cancers." (PMID 36513999, 2022). "Finally, the tumor xenograft model was applied to validation the role of SCARA5 tumor growth inhibition in vivo." (PMID 36513999, 2022). "The reasons for our results might be as follows: first, SCARA5 might have been mutated in ESCC, leading to the transformation of a tumor suppressor gene into a tumor promoter gene." (PMID 35755171, 2022).